AGO1 (argonaute RISC component 1)
Diseases named in the same sentence as AGO1 in open-access papers (continued):
Sharing a sentence is not in itself a finding about the gene and the disease.
breast carcinoma (11 papers, 2015 to 2026). "The study did not signal a significant impact of AGO2 SNPs; however, rs595055 C/T, one of the AGO1 genetic variants, was associated with augmented breast cancer risk." (PMID 33668654, 2021). "Also, breast cancer cells that escape from therapy-induced senescence express high levels of AGO1x, a TR isoform of AGO1 linked to breast cancer progression." (PMID 34676390, 2021). "Moreover, one report points to the tumor-promoting activity of AGO1x, a translational readthrough variant of AGO1, dependent on nuclear scattering of dsRNAs and silencing of interferon-induced apoptosis in breast cancer cells." (PMID 33668654, 2021). "Further studies on the influence of AGO1 and AGO2 SNPs on breast cancer susceptibility were conducted on 93 Mediterranean cases and uncovered another AGO1 SNP (rs636832 A/A), as well as one more AGO2 (rs2977490 G/G) variant associated with elevated risk of the disease." (PMID 33668654, 2021). "Furthermore, the AGO1 rs595055 polymorphism has been associated with low breast cancer risk in Russians." (PMID 32503341, 2020). "Here, we investigated the effects of endothelial-specific AGO1 knockout (EC-AGO1-KO) on tumor vascularization and immune regulation in a mouse syngeneic breast cancer model induced by E0771 cells." (PMID 42286210, 2026). "For example, it has been reported that ERα directly inhibits Drosha and that Exportin 5, Dicer1, Ago1, and Ago2 are low in ERα positive breast cancers." (PMID 33477993, 2021). "Single-Nucleotide Polymorphisms (SNPs) of AGO1 and AGO2 genes were found to be related to Disease-Free Survival (DFS) and Overall Survival (OS) in breast cancer in order to risk impact of renal cell carcinoma." (PMID 32503341, 2020). "Conversely, Ago1/2 were found to be downregulated in ER+ breast cancers versus ER− breast cancers despite upregulation of other components of the RISC (i.e. Dicer and TRBP)." (PMID 30214383, 2018). "AGO1 could control cell and tissue growth, and affected the progression of multiple types of cancers, such as breast cancer and liver cancer." (PMID 33832481, 2021). "In addition, we show that cells that escape from senescence increase the expression of AGO1x, an endogenous TR isoform of AGO1 that suppress the interferon pathway stimulating cell proliferation in breast cancer cells." (PMID 34676390, 2021). "Together, these findings identify endothelial AGO1 as a key regulator of tumor vasculature and immune homeostasis in breast cancer, suggesting that targeting endothelial AGO1 may represent a novel therapeutic strategy to modulate tumor vasculature while enhancing anti-tumor immunity." (PMID 42286210, 2026). "To thoroughly characterize the specificity of this antibody, we examined the expression of both AGO1 and AGO1x in the MDA‐MB‐231 breast cancer cell line upon perturbations." (PMID 32812257, 2020). "There are four argounatue (AGO) proteins in humans AGO1–4 and evaluation of alterations in AGO1–4 gene expression across breast cancer cell lines and tumor samples has shown that AGO2 is increased in ER− samples versus ER+ while there is no change in AGO1, AGO3, or AGO4." (PMID 26062653, 2015).
hepatocellular carcinoma (8 papers, 2015 to 2024). A malignant tumor that arises from hepatocytes. "TRIM71 promoted proliferation of several hepatocellular carcinoma (HCC) cell lines presumably via ubiquitylation-mediated AGO1/2 protein destabilization." (PMID 31732746, 2019). "AGO1 may regulate HCC (hepatocellular carcinoma) cell growth and metastasis through the TGF-β pathway." (PMID 38329551, 2024). "HepG2 (human hepatoma) cells showed high AGO1 mRNA expression." (PMID 27518285, 2016). "AGO1 could influence the prognosis of hepatocellular carcinoma (HCC) through TGF-β pathway." (PMID 33832481, 2021). "In hepatocellular carcinomas, a correlation between activation of the EMT process and AGO1 has been identified." (PMID 33668654, 2021). "The aim of our study was to investigate AGO1 functions in hepatocellular carcinoma (HCC)." (PMID 29487329, 2018).
Intellectual disability (7 papers, 2017 to 2025). "Recently, pathogenic variants and gross deletions involving AGO1 have been associated with neurodevelopmental disorders in humans, including autism spectrum disorder, developmental delay, intellectual disability, and dysmorphic facial features." (PMID 41465536, 2025). "These AGO1 variants, including missense mutations and small deletions, were associated with intellectual disabilities and other common clinical features seen in AGO-related disorders." (PMID 39457367, 2024). "AGO1 mutations have been identified in patients with intellectual disability or autism spectrum disorder." (PMID 35736234, 2022). "De novo mutations in Argonaute 1 (AGO1) have been detected in individuals with intellectual disability or ASD." (PMID 33802132, 2021). "In addition, several studies reported typical facial features among patients with intellectual disabilities whose genomes have a mutation on the AGO1 gene." (PMID 35736234, 2022). "Thereby, AGO1 mutations may serve as causality for the syndromic form of intellectual disability/autism-spectrum disorder." (PMID 32503341, 2020). "Furthermore, AGO1 genomic alterations present a causal link to intellectual disability/autism spectrum disorder." (PMID 32503341, 2020). "Genetic variants in AGO1 and AGO2 have been associated with a range of neurodevelopmental disorders (NDDs), including intellectual disability, developmental delays, and speech impairments." (PMID 39457367, 2024).
developmental delay (5 papers, 2016 to 2025). "Microdeletions of the chromosomal region encoding AGO1 and AGO3 genes were found in five patients with hypotonia, poor feeding, and developmental delay, suggesting the possibility that AGO1 and AGO3 are involved in neurocognitive deficits." (PMID 35736234, 2022). "The AGO1 (OMIM 606228) and AGO3 (OMIM 607355) genes when deleted have been hypothesized to be associated with developmental delays, hypotonia, and poor feeding." (PMID 29726122, 2018). "All three had a history of motor and speech delays of unknown severity; however their deletions also included the AGO1 and AGO3 genes which have been hypothesized to be associated with developmental delays, hypotonia, and poor feeding." (PMID 29726122, 2018). "More precisely, GLUT1 deficiency may cause a specific syndrome which correlates with hyperactivity and developmental delay, RIMS3 is considered to be a novel candidate for autism, GRIK3 has also been associated with developmental delay, and AGO1/AGO3 may be responsible for neurocognitive deficits." (PMID 27713767, 2016).
lung carcinoma (5 papers, 2011 to 2023). "Further genotyping experiments, including 622 Korean lung cancer cases, revealed a protective effect of the rs636832 A > G AGO1 variant." (PMID 33668654, 2021). "Based on the analysis of 473 Chinese patients’ DNA, the rs595961 AG genetic variant of AGO1 was found to correlate with elevated susceptibility of lung carcinomas." (PMID 33668654, 2021). "Herein, we evaluated the association between five SNPs in GEMIN4 and AGO1, the gene-environment interaction and lung cancer risk." (PMID 27669275, 2016). "Recently, a SNP haplotype in the miRNA biogenesis gene RNASEN was associated with shorter survival in lung cancer, and a SNP in another biogenesis-related compound, AGO1 rs636832, was linked to a decreased risk of lung cancer." (PMID 21799879, 2011). "AGO1 polymorphisms have also been assessed as an influence on lung cancer risk." (PMID 33668654, 2021). "Here, we selected five single nucleotide polymorphisms (SNPs) (rs7813, rs2740349, rs2291778, rs910924, rs595961) in two key microRNA biosynthesis genes (GEMIN4 and AGO1) and systematically evaluated the association between these SNPs, the gene-environment interaction and lung cancer risk." (PMID 27669275, 2016). "Collectively, these results showed AGO1 knockdown inhibited the proliferation, and motility of lung cancer cells in vitro." (PMID 33832481, 2021). "Subsequently, CCK-8 and colony formation assays showed AGO1 ablation suppressed the proliferation of lung cancer cells." (PMID 33832481, 2021). "Collectively, these results showed that POU2F2 promoted tumor growth of lung cancer cells via AGO1 in mice." (PMID 33832481, 2021). "As a comparison, we found POU2F2 depletion inhibited the expression of AGO1 in two types of lung cancer cells." (PMID 33832481, 2021). "We then investigated the effects of AGO1 on the proliferation, migration, and invasion of lung cancer cells in vitro." (PMID 33832481, 2021). "Our data confirmed that POU2F1 transcriptionally activated AGO1 and therefore promoted the progression of lung cancer, and the precise molecular mechanisms and the signaling pathways need further study." (PMID 33832481, 2021). "We further demonstrated POU2F2 could promote the proliferation and motility of lung cancer cells through transcriptionally activating AGO1, and fascinate tumor growth of lung cancer cells in mice." (PMID 33832481, 2021). "We also found POU2F2 could promote the proliferation, and motility of lung cancer cells via AGO1, and contribute to tumor growth of lung cancer cells in mice." (PMID 33832481, 2021). "Then we explored whether POU2F2 promoted the proliferation, migration, and invasion of lung cancer cells via AGO1." (PMID 33832481, 2021). "The effects of AGO1 in the progression of lung cancer has been widely revealed." (PMID 33832481, 2021). "POU2F2 promoted the proliferation, and motility of lung cancer cells via targeting AGO1 in vitro." (PMID 33832481, 2021). "Therefore, we thought POU2F2 promoted the proliferation, migration, and invasion of lung cancer cells via targeting AGO1." (PMID 33832481, 2021). "Additionally, POU2F2 promoted tumor growth of lung cancer cells via AGO1 in vivo." (PMID 33832481, 2021). "In summary, POU2F2 could promote the expression of AGO1 in lung cancer cells." (PMID 33832481, 2021). "However, when the sequence of site 1 was mutant, POU2F2 overexpression could hardly stimulate the luciferase activity of AGO1 in lung cancer cells, further confirming our conclusion." (PMID 33832481, 2021). "We here found the involvement of AGO1 in lung cancer progression, and further confirmed that POU2F2 regulated lung cancer progression via AGO1." (PMID 33832481, 2021).
colon cancer (4 papers, 2010 to 2021). "The prognostic value of AGO1 has been implicated in colon cancer." (PMID 33668654, 2021). "It has been reported AGO1 acted as a biomarker for colon cancer, melanoma, and muscle-invasive bladder carcinomas." (PMID 33414440, 2021). "The upregulation of AGO1 was inversely correlated with survival rates of colon cancer patients, based on the assessment of 75 cases." (PMID 33668654, 2021). "Recent studies have revealed that Ago1 and Ago2 play an important oncogenic role in breast and colon cancer." (PMID 28977858, 2017).
depression (4 papers, 2019 to 2024). "This is associated with a variety of diseases, including depression, and can alter an individual’s susceptibility to the disease; for examples microRNA processing genes DGCR8 rs3757 and AGO1 rs636832 are significantly associated with depression." (PMID 38711022, 2024). "The aim of our research was to assess the relationship between the occurrence of depression and the presence of SNPs in genes AGO1 (rs636882) and AGO2 (rs4961280; rs2292779; rs2977490) in a Polish population." (PMID 36142498, 2022). "In our work, we looked for a relationship between AGO1 and AGO2 polymorphisms and the risk of depression." (PMID 36142498, 2022). "Thus, the aim of the author’s own research was to assess the relationship between the occurrence of depression and the presence of SNP in genes: AGO1 (rs636882) and AGO2 (rs4961280; rs2292779; rs2977490)." (PMID 36142498, 2022). "They discovered that AGO1 rs636832 was significantly associated with depression and that GEMIN4 rs7813 did not affect susceptibility to depression." (PMID 36405016, 2022).
gastric cancer (4 papers, 2013 to 2021). A primary or metastatic malignant neoplasm involving the stomach. "The present study investigates the influence of genetic variants in miRNA machinery genes (DROSHA, DICER, AGO1, and GEMIN4) on gastric cancer in Chinese Han population, further revealing the genetic mechanisms of gastric cancer occurrence and development." (PMID 29156806, 2017). "Our evidence indicated that AGO1 was enriched surrounding the binding site of miR-558 within HPSE promoter in gastric cancer cells." (PMID 27685626, 2016). "The ChIP and real-time quantitative PCR (qPCR) assay revealed that in cultured gastric cancer cells, enrichment of AGO1 was observed at the region (−2347/−2148 bp), which was surrounding the binding site of miR-558." (PMID 27685626, 2016). "Collectively, these data suggested that miR-558 recognized the target site to activate the HPSE transcription in an AGO1-dependent manner in gastric cancer cells." (PMID 27685626, 2016). "Given that hsa-miR-103a-3p responded to hypoxia and targeted argonaute 1 (AGO1) to promote angiogenesis, and EXO-miR-103a increases angiogenesis in gastric cancer targeting c-MYB, downregulation of exosomal hsa-miR-103a-3p in the BPD group is likely to suppress fetal angiogenesis." (PMID 33842462, 2021). "Since AGO1 is important for active chromatin remodelling at gene promoters induced by miRNA,41 we further observed the functions of AGO1 in miR-558-activated expression of HPSE in gastric cancer." (PMID 27685626, 2016). "In addition, knockdown of AGO1 attenuated the increase in promoter activity and nascent transcription of HPSE induced by over-expression of miR-558 in gastric cancer cells." (PMID 27685626, 2016). "A Korean study of 2010 evaluated AGO1, AGO2, TNRC6A, TNRC6C, TARBP2 and XPO5 mutations in colorectal (CRC) and gastric cancers (GC), with or without microsatellite instability." (PMID 23586049, 2013). "In addition, treatment of gastric cancer cells with RNase H, but not with RNase A, inhibited the enrichment of AGO1 on the HPSE promoter." (PMID 27685626, 2016). "Knockdown of AGO1, but not of Argonaute 2 (AGO2), Argonaute 3 (AGO3) or Argonaute 4 (AGO4), abolished the miR-558-facilitated protein and transcriptional levels of HPSE in gastric cancer cells." (PMID 27685626, 2016).
Obesity (4 papers, 2018 to 2022). Accumulation of substantial excess body fat. "Based on the theoretical notions above, some angiogenesis inhibitors, such as endostatin and AGO1, have been found to resist obesity, whereas proangiogenic factors such as ANT-2 exert anti-obesity effect." (PMID 35067158, 2022). "Taken together, these data indicate that inactivation of Ago2, but not Ago1, in the liver increases mitochondrial capacity and energy expenditure, which appears to link to improvement of obesity-associated pathophysiology." (PMID 30201950, 2018). "Hepatic Ago1 is dispensable for obesity-induced pathophysiology, as deletion of hepatic Ago1 did not affect diet-induced weight gain, glucose tolerance, or insulin sensitivity." (PMID 30201950, 2018).
ovarian carcinoma (4 papers, 2014 to 2021). A malignant neoplasm originating from the surface ovarian epithelium. "Moreover, correlation analysis revealed that the PVT1 expression was associated with AGO1 expression in ovarian cancer tissues." (PMID 34288373, 2021). "Taken together, the present study reveals that PVT1/miR‐148a/AGO1 axis plays an important role in the progression of ovarian cancer and emphasize the potential as a target of value for ovarian cancer therapy." (PMID 34288373, 2021). "Overall, these findings reveal that the expression of AGO1 was modulated through PVT1/miR‐148a‐3p axis in ovarian cancer." (PMID 34288373, 2021). "In our study, we revealed that PVT1 expression was significantly increased in ovarian cancer tissues which is associated with advanced FIGO stage, lymph‐node metastasis, poor survival rate and high expression of AGO1." (PMID 34288373, 2021). "Our data suggest that PVT1 promotes ovarian cancer metastasis through PVT1/miR‐148a‐3p/AGO1/TGF‐β axis." (PMID 34288373, 2021). "Our results also demonstrate that AGO1 knockdown suppress the ovarian cancer progression both in vitro and in vivo." (PMID 34288373, 2021). "We reveal that PVT1 expression was significantly increased in ovarian cancer tissues which is associated with advanced FIGO stage, lymph‐node metastasis, poor survival rate, and high expression of AGO1." (PMID 34288373, 2021). "In conclusion, our findings provide insight into PVT1/miR‐148a‐3p/AGO1 axis to be a novel therapy target for human ovarian cancer." (PMID 34288373, 2021). "In this study, we aimed to determine the PVT1 and AGO1 expression in human ovarian cancer tissues and cell lines." (PMID 34288373, 2021). "Previous studies identified an association between AGO1 and AGO2 and ovarian carcinoma, myeloma angiogenesis, as well as with an angiogenesis defect model related to inflammation." (PMID 31724726, 2019). "Higher expression levels of AGO1 and AGO2 associated with tumor progression have been found in different cancer entities, such as in epithelial skin cancer and ovarian cancer." (PMID 29857476, 2018). "The study group saw similar trends for both Ago1 and Ago2 with respect to overall survival, suggesting a pivotal role of these molecules in ovarian cancer progression." (PMID 25295252, 2014). "Similarly, declined AGO1 expression in ovarian cancer cell line was accompanied by a greater distance between the two wound fronts compared to scramble group, as determined by the wound‐healing assay." (PMID 34288373, 2021). "However, the effects of AGO1 on ovarian cancer, and the relationship between PVT1 and AGO1 are currently unclear and therefore need to be explored." (PMID 34288373, 2021). "For example, we studied the TGF‐β pathway downstream the PVT1/miR‐148a‐3p/AGO1 signalling; however, there may be other pathways that are also participate in the regulatory roles of this axis on ovarian cancer cells, which are also worth studying." (PMID 34288373, 2021). "In our study, we reveal the downstream mechanism of miR‐148a‐3p in ovarian cancer is related to the negative regulation of AGO1 through bioinformatics analysis and dual luciferin report experiment, which expands the functional roles of miRNA‐148a‐3p in ovarian cancer." (PMID 34288373, 2021). "All of these studies indicate that miRNA may act as an intermediary bridging PVT1 and AGO1 to regulate the ovarian cancer progression." (PMID 34288373, 2021). "We next determined the effects of PVT1/miR‐148a‐3p/AGO1 axis on the ovarian cancer cell functions." (PMID 34288373, 2021). "Importantly, we also investigated the roles of AGO1 in ovarian cancer, a protein highly expressed and closed related to the tumour progression." (PMID 34288373, 2021). "To further verify that AGO1 modulated the ovarian cancer cell functions via ERK1/2 not P38, we used the ERK1/2 inhibitor (LY3214996) and P38 inhibitor (SB203580) to inactivate the phosphorylation of ERK1/2 and P38, respectively." (PMID 34288373, 2021).
ovarian carcinoma (continued). "Furthermore, we discovered that PVT1 up‐regulated the expression of AGO1 and thus regulated the transforming growth factor‐β (TGF‐β) pathway to promote ovarian cancer progression through sponging miR‐148a‐3p." (PMID 34288373, 2021). "Additionally, in our study, we only demonstrate the important regulatory effects of PVT1/miR‐148a‐3p/AGO1 axis in SKOV3 cell line, and other ovarian cancer cell lines such as A2780, COC1, OVCAR3 and CAOV3 should also be further investigated." (PMID 34288373, 2021).